HOXA6 (homeobox A6)
Diseases named in the same sentence as HOXA6 in open-access papers:
HOXA6 is named in the same sentence as 31 diseases in open-access papers, as found by Europe PMC text mining. Sharing a sentence is not in itself a finding about the gene and the disease. The quoted sentences say what the papers report.
colorectal cancer (7 papers, 2019 to 2025). A primary or metastatic malignant neoplasm that affects the colon or rectum. "HOXA6 expression is dysregulated in multiple cancers, including renal cancer, colorectal cancer and glioma." (PMID 40105492, 2025). "In gastric cancer and colorectal cancer, HOXA6 can inhibit the apoptosis of tumor cells by binding to other genes or acting on other pathways to promote the occurrence and progression of tumors." (PMID 40538732, 2025). "In colorectal cancer cells, upregulation of HOXA6 promoted cell proliferation, migration, and invasion and inhibited apoptosis." (PMID 37547473, 2023). "Some evidence shows that HOXA6 genes are deregulated in multiple cancers, such as cervical cancer, cerebral glioma, renal cancer and colorectal cancer (CRC)." (PMID 33535170, 2021). "High HOXA6 expression is previously discovered in some tumors, for instance, cervical cancer and colorectal cancer." (PMID 33535170, 2021). "Similar to this result, downregulation was also observed for the HOXA2 and HOXA6 genes in large-scale human colorectal cancer expression databases." (PMID 31165042, 2019). "HOXA5, HOXA2, and HOXA6 are frequently methylated, and this leads to silencing of these genes and progression of colorectal cancer." (PMID 31165042, 2019). "This indicated that hypermethylation of HOXA5, HOXA2, and HOXA6 is an important event in colorectal cancer." (PMID 31165042, 2019). "So, more research is needed in future to confirm the true role of HOXA6 in colorectal cancer." (PMID 31165042, 2019). "HOXA6 is a member of the HOX family and its expression is dysregulated in colorectal cancer, renal cancer, glioma and gastric cancer." (PMID 40105492, 2025). "In colorectal cancer, the percentage of methylation of three HOXA genes (HOXA5, HOXA2, and HOXA6) were up to 67.62%, 58.36%, and 31.32%, respectively." (PMID 36159969, 2022). "In this article, based on the latest colorectal cancer database and our experiments, we analyze the methylation status in three HOXA genes including HOXA2, HOXA5, and HOXA6 and its clinical application." (PMID 31165042, 2019). "HOXA6 and HOXA13 promote gastric cancer and colorectal cancer." (PMID 37834206, 2023). "All indicated promoter methylation may be responsible for the silencing of 3 HOXA genes in colorectal cancer, especially the HOXA5 and HOXA6." (PMID 31165042, 2019). "Additionally, the correlation analysis in TCGA and our colorectal cancer tissues showed a significant negative correlation between methylation levels and the expression of HOXA5 and HOXA6 genes." (PMID 31165042, 2019).
glioma (5 papers, 2021 to 2025). A benign or malignant brain and spinal cord tumor that arises from glial cells (astrocytes, oligodendrocytes, ependymal cells). "One study found that the suppression of HOXA6 expression could reduce invasion tendency in glioma cell lines of U-118 and U-138." (PMID 37547473, 2023). "HOXA6 and HOXC5 IHC staining was weak in the normal brain tissues, while glioma tissue exhibited strong HOXA6 and HOXC5 IHC staining." (PMID 37547473, 2023).
gastric cancer (4 papers, 2021 to 2025). A primary or metastatic malignant neoplasm involving the stomach. "Ectopic expression of HOXA6 promoted the growth, clone formation, migration and invasion capacity of gastric cancer cells, as shown by gain- and loss-of-function experiments." (PMID 33535170, 2021). "These experiments suggest that the positively expression of HOXA6 is associated with PBX2 expression in gastric cancer." (PMID 33535170, 2021). "Our present work first analyzed the role HOXA6 in GC and exhibited that HOXA6 was upregulated in human gastric cancer clinical specimens in comparison to normal gastric tissues." (PMID 33535170, 2021). "This work high HOXA6 levels in most of gastric cancer tissues compared to matched normal gastric tissues by tissue microarray." (PMID 33535170, 2021). "For determining the synergistic effect of HOXA6 and PBX2 on promoting gastric cancer cell invasion and migration, we examined the effect of HOXA6 or PBX2 overexpression or knockdown with siRNA." (PMID 33535170, 2021). "Correlation between HOXA6 protein expression and the clinicopathological parameters of gastric carcinoma." (PMID 33535170, 2021). "Moreover, HOXA6 boosts gastric cancer cell migration, invasion, and proliferation." (PMID 33535170, 2021). "Moreover, HOXA6 physically interacts with PBX2, and the coexpression of HOXA6 and PBX2 promotes gastric cancer cell migration and invasion." (PMID 33535170, 2021). "Notably, the expression of HOXA6 in gastric cancer tissues were clearly higher than those in matched normal nontumorous tissues in a large sample dataset from the TCGA database (637 samples)." (PMID 33535170, 2021).
meningioma (4 papers, 2013 to 2024). A generally slow growing tumor attached to the dura mater. "Within the PCR-targeting genes, DNA hypermethylation of HOXA6 and HOXA9 has also been implicated in recurrent meningiomas according to another study." (PMID 23349797, 2013). "Genes with hypermethylated CpG islands in malignant meningiomas (such as HOXA6 and HOXA9) tend to coincide with the binding sites of polycomb repressive complexes (PRC) in early developmental stages." (PMID 23349797, 2013). "For the malignant meningiomas in our study, 26 genes were identified as significantly hypermethylated at promoter CpG islands, including eight genes involved in the biological pathway of neurogenesis (BARHL2, TLX3, FOXR1, HOXA11, HOXA6, HOXA9, OTX2 and PAX3)." (PMID 23349797, 2013).
breast cancer (3 papers, 2020 to 2023). A primary or metastatic malignant neoplasm involving the breast. "Notably, ceRNAs of miR-1294 have not been found in Breast cancer (BC), ccRCC, OC, and low expression of miR-1294 can relax the repression of HOXA6, IGF1R, thereby promoting cancer risk." (PMID 37303740, 2023).
cervical cancer (3 papers, 2017 to 2021). A primary or metastatic malignant neoplasm involving the cervix. "In particular, the upregulation of the HOXA1, HOXA5, and HOXA6 genes were found to be significantly associated with unfavorable overall survival in patients with cervical cancer." (PMID 29137433, 2017). "In conclusion, in this study, we showed that the upregulation of the expression of the HOXA1, HOXA5, and HOXA6 genes are significantly associated with unfavorable overall survival as well as increased mortality in a large cohort of cervical cancer cases from TCGA database." (PMID 29137433, 2017). "Upregulated HOXA1, HOXA5, and HOXA6 expression are significantly correlated with unfavorable overall survival and increased mortality in cervical cancer patients." (PMID 29137433, 2017). "In this study, we showed that the increased mRNA expression of four HOX genes—HOXA1, HOXA5, HOXA6, and HOXC11—is independently associated with mortality in cervical cancer based on data from TCGA." (PMID 29137433, 2017).
clear cell renal cell carcinoma (3 papers, 2022 to 2023). "Furthermore, miR-1294 was downregulated in ovarian cancer (OC) and clear cell renal cell carcinoma (ccRCC), thereby relaxing its repressive effects on insulin-like growth factor 1 receptor (IGF1R) and homeobox A6 (HOXA6)." (PMID 37303740, 2023).
leukemia (3 papers, 2019 to 2025). A malignant (clonal) hematologic disorder, involving hematopoietic stem cells and characterized by the presence of primitive or atypical myeloid or lymphoid cells in the bone marrow and the blood. "It was confirmed that re‐expression of Hoxa6 can partly rescue the leukemia initiation defect caused by Ddit4 deletion." (PMID 40621878, 2025). "Mechanistically, DDIT4 upregulates the expression of HOXA gene cluster, and re‐expression of HOXA6 in DDIT4 knockout AE9a cells can rescue the impaired leukemia initiation." (PMID 40621878, 2025). "AE9a‐Ddit4−/− GFP+ leukemia cells were retrovirally transduced with Hoxa6‐RFP expressing construct (MSCV‐Hoxa6‐IRES‐RFP) or empty vector (MSCV‐IRES‐RFP)." (PMID 40621878, 2025). "As expected, AE9a‐Ddit4−/−Hoxa6 cell‐transplanted mice developed leukemia with a significantly shorter survival time (median survival: 53 days) compared with AE9a‐Ddit4−/−Vec mice, indicating that re‐expression of Hoxa6 in AE9a‐Ddit4−/− cells accelerated leukemia development." (PMID 40621878, 2025).
endometrial cancer (2 papers, 2019 to 2022). Primary or metastatic malignant neoplasm involving the endometrium (mucous membrane that lines the endometrial cavity). "Also, poor prognosis of patients with endometrial cancer is associated with higher levels of HOXA4, HOX5, HOXA6, HOXA7, and HOXB9 expression, whereas favorable prognosis of patients with endometrial cancer is associated with higher levels of HOXB5 and HOXB6 expression." (PMID 30866492, 2019).
lymph node metastasis (2 papers, 2017 to 2021). "The upregulation of HOXA6 was closely associated with differentiation, lymph node metastasis, AJCC stage, TNM stage, and poor survival outcome in GC patients based on tissue microarray (TMA) data." (PMID 33535170, 2021). "Overall mortality was significantly associated with advanced FIGO stage, lymph node metastasis, lymphovascular invasion, and increased HOXA1, HOXA5, HOXA6, and HOXC11 mRNA expression." (PMID 29137433, 2017).
acute myeloid leukemia (1 paper, 2021). Acute myeloid leukemia (AML) is a group of neoplasms arising from precursor cells committed to the myeloid cell-line differentiation. "Moreover, HOXA6 was upregulated in patients with acute myeloid leukemia." (PMID 33535170, 2021).
asthma (1 paper, 2020). "For the remaining genes (airway fibroblasts: HOOK2 and HOXA7; parenchymal fibroblasts: HOXA5, HOXA6, HOXA-AS3, RB1 and NR2F1-AS1), there was no differential gene expression between donors with and without asthma." (PMID 33008450, 2020).
Down syndrome (1 paper, 2024). "Concerning the fourth gene HOXA6, we performed univariate logistic regressions of the Down syndrome outcome on each of the 20 CpG sites located in the genetic region, and only identified one significant CpG site (p -value of 0.018)." (PMID 39290359, 2024).
lung adenocarcinoma (1 paper, 2023). A carcinoma that arises from the lung and is characterized by the presence of malignant glandular epithelial cells. "In vitro, HOXA6 promoted cell proliferation, migration, and invasion in lung adenocarcinoma (LUAD)." (PMID 37547473, 2023).
lung carcinoma (1 paper, 2023). "NRP1 regulation of radioresistance in lung cancer involves downstream homeobox genes HOXA6 and HOXA9, and microRNA-9 is able to restore radio-sensitivity in radioresistant lung cancer cells by targeting NRP1." (PMID 37894289, 2023).
melanoma (1 paper, 2024). A malignant, usually aggressive tumor composed of atypical, neoplastic melanocytes. "Many studies have demonstrated over- or under-expression of particular types of lncRNAs, such as HOXA6, FDG5-AS1, PVT1, and NKILA in patients with melanoma as a result of developments in sequencing methods." (PMID 39777348, 2024).
mesothelioma (1 paper, 2023). A usually malignant and aggressive neoplasm of the mesothelium which is often associated with exposure to asbestos. "The expression and chromatin analyses at genes such as USP43, HOXA6, HOXA10, and USP18 demonstrate that these genes are downregulated via PRC2-mediated silencing in BAP1-deficient mesothelioma." (PMID 36657447, 2023).
neuropathy (1 paper, 2021). A disorder affecting the nervous system that manifests with pain, tingling, numbness, and/or muscle weakness. "The researchers found that TET1 up-regulation indirectly acts on Homeobox A6 protein (HOX-A6) expression in neurons, thus becoming a pivotal target in ameliorating oxaliplatin-induced neuropathy." (PMID 34026827, 2021).
prostate carcinoma (1 paper, 2023). A carcinoma that arises from epithelial cells of the prostate gland. "HOXA13, HOXA1, HOXA5, HOXA6, HOXA7, HOXA9, and HOXA10 are involved in prostate cancer, and they form a DNA loop with a locus that induces prostate cancer and regulates gene transcription." (PMID 37590265, 2023).
pyometra (1 paper, 2009). "The strong downregulation of homeobox genes in dogs afflicted with pyometra was also verified by qPCR analysis, as shown for MSX2 and HOXA6." (PMID 19956711, 2009).
tumor (13 papers, 2018 to 2025). "To further clarify the mechanism by which DDR1 regulates ferroptosis in BC cells, we performed RNA‐seq on TCCSUP cells and HOXA6, a tumour‐associated gene." (PMID 40105492, 2025). "In order to provide clinicians with predicted prognosis of LGG patients quantitatively, we constructed the nomogram combining HOXA1, HOXA6 expression and independent clinical risk factors (tumor grade, age, primary therapy outcome and age)." (PMID 35349479, 2022). "HOXA5 methylation was associated with age, T, M, stage, and tumor status, and HOXA6 methylation was associated with age and KRAS mutation." (PMID 31165042, 2019). "Furthermore, HOXA5 methylation was shown to be associated with age, stage, and tumour status, while HOXA6 methylation was linked to age and KRAS mutation." (PMID 35054365, 2022). "Some studies have shown that HOXA6 promotes the malignant phenotypes of tumour cells, such as proliferation, migration and invasion, whereas others have confirmed that HOXA6 inhibits tumour cell proliferation and promotes apoptosis." (PMID 40105492, 2025). "Univariate and multivariate analyses revealed that HOXA1, HOXA6 expression and tumor grade, age, primary therapy outcome and age were independent factors affecting the prognosis of LGG patients." (PMID 35349479, 2022). "For better exploring the effect of HOXA6 on tumor metastasis in vivo, we adopted the AGS cell pulmonary metastasis model in the present work." (PMID 33535170, 2021). "However, after DDR1 knockdown, tumour growth was inhibited, and HOXA6 overexpression reversed the action of DDR1 silencing." (PMID 40105492, 2025). "Additionally, the multivariate analyses revealed that HOXA1, HOXA6 expression and tumor grade, age, primary therapy outcome and age were independent factors affecting the prognosis of LGG patients." (PMID 35349479, 2022). "HOXA6 played a crucial part in tumor metastasis and invasion, we questioned whether HOXA6 synergizes with PBX2 to promote GC metastasis." (PMID 33535170, 2021). "Consequently, we suspected that the effects of HOXA-AS3 on tumor cell proliferation were mediated by changes in the levels of HOXA6." (PMID 29899328, 2018). "The percentage of methylation in the HOXA5, HOXA2, and HOXA6 genes in CRC were up to 67.62, 58.36, and 31.32%, respectively, and ranked first in CRC among all human tumor tissues." (PMID 31165042, 2019). "Among these genes, six (HOXA6, STC2, HSD17B8, TFAP2A, CYP1B1, and HOXC8) were reported to be osteogenesis-/chondrogenesis-related genes, and five (ADRA1A, TSPYL5, TES, TNFRSF10D, and MBP) were reported to be tumor-suppressor genes." (PMID 31889115, 2019). "Comparing benign to tumour samples, HOXA6 (p = 4.26 × 10−5), HOXB6 (p = 0.001), HOXC5 (p = 4.69 × 10−5), HOXC6 (p = 3.02 × 10−28), and HOXC9 (p = 0.0001) all showed significantly greater expression in tumour samples, with HOXC6 having by far the greater fold difference." (PMID 40725480, 2025). "Next, we detected the expression of HOXA6 and PBX2 in 23 gastric mucosa tumor tissue specimens and adjacent nontumor tissue by IHC staining." (PMID 33535170, 2021).
cancer (10 papers, 2010 to 2025). A tumor composed of atypical neoplastic, often pleomorphic cells that invade other tissues. "Multiple enriched genes (Hoxa6, Hoxa10, and Meis1) in the pathway of transcriptional misregulation in cancer were associated with LSC self-renewal and survival." (PMID 36593968, 2023). "Pearson correlation analysis showed that HOXA6 level showed positive association with PBX2 level within cancer tissues." (PMID 33535170, 2021). "High expression of genes such as HOXB5, HOXC11, HOXA13, HOXD13, HOXA6, and HOXC6 in certain cancers is linked to poor overall survival (OS)." (PMID 39980564, 2025). "Relative to cells that expressed vector, F-actin fibers were detected in cells with HOXA6 over-expression, which participated in cancer cell metastasis and invasion that were concentrated mainly just inside the cytoplasm and margin." (PMID 33535170, 2021). "Semiquantitative scoring showed that HOXA6 protein level increased within GC tissue samples relative to matched non-carcinoma samples." (PMID 33535170, 2021). "HOXA6 is up-regulated in various cancers, which suggests that the over-expressed HOXA6 level may promote GC development." (PMID 33535170, 2021). "Moreover, HOXA6 was up-regulated while E-cadherin was down-regulated within cancer tissues relative to non-carcinoma samples of nude mice, as demonstrated by IHC and q-PCR assays." (PMID 33535170, 2021). "In our article, we found that HOXA5 and HOXA6 were more likely to be methylated in patients < 60 years of age, so these two genes may serve as screening indexes for younger cancer patients." (PMID 31165042, 2019). "The DNA methylation profiles of the 3 HOXA gene promoter regions were downloaded from TCGA, and the results demonstrated that the methylation levels of HOXA5, HOXA2, and HOXA6 were significantly elevated in cancer tissues compared with normal tissues (p < 0.0001)." (PMID 31165042, 2019). "We suspected that HOXA-AS3 might promote cancer cell proliferation migration and invasion by interacting with HOXA6, so we further characterized the function of HOXA6 in A549 cells, and the efficiency of HOXA6 silencing was determined." (PMID 29899328, 2018). "In addition, HOXA6 regulates the proliferation, migration and invasion of cancer cells; however, its role in ferroptosis remains unknown." (PMID 40105492, 2025). "We found that the methylation percentages of HOXA5, HOXA2, and HOXA6 in CRC tissue were up to 67.62, 58.36, and 31.32%, respectively, and ranked first in CRC among all cancer types analyzed." (PMID 31165042, 2019). "For promoter-associated CpG islands, a number of them, including those of NTF3, FGF, OSR1, HOXA6, NPY and WT1, have previously been reported as differentially methylated in other cancer types." (PMID 20051947, 2010). "In addition, HOXA6 and PBX2 levels were markedly up-regulated within GC samples compared with the matched non-carcinoma samples." (PMID 33535170, 2021).
HOXA6 also shares sentences with these, for which no sentence is quoted: renal carcinoma (2 papers); Bladder Cancer (1); colorectal adenocarcinoma (1); congenital heart defects (1); malignant lymphoma (1); neuroblastoma (1); ovarian carcinoma (1); pancreatic neuroendocrine neoplasm (1); squamous cell carcinoma (1).